IL6R (interleukin 6 receptor)
Diseases named in the same sentence as IL6R in open-access papers (continued):
Sharing a sentence is not in itself a finding about the gene and the disease.
rheumatoid arthritis (continued). "For example, the humanized anti-IL-6R antibody tocilizumab is FDA-approved for the treatment of rheumatoid arthritis, certain autoimmune disease, and severe or life-threatening CAR-T cell-induced cytokine release syndrome." (PMID 36551971, 2022). "IL-6 and the IL-6 receptor (IL-6R) axis contribute to various autoimmune diseases, and their inhibition has shown considerable effects in such cases as rheumatoid arthritis." (PMID 36285981, 2022). "We treated MDSL cells with tocilizumab, a monoclonal antibody against IL-6R that is clinically used to treat rheumatoid arthritis." (PMID 35900794, 2022). "This variant was also associated with a decreased odds of coronary heart disease events, the effect of which was consistent with IL6R blockade from infusions of tocilizumab in patients with rheumatoid arthritis studied in randomized trials." (PMID 34977172, 2021). "Of these, tocilizumab/Actemra and sarilumab/Kevzara antibodies capable of binding to the interleukin-6 receptor (IL-6R) and promoted for therapy of rheumatoid arthritis can be repurposed for Covid-19 therapy." (PMID 34358177, 2021). "The human anti-IL-6 receptor (IL-6R) antibody tocilizumab (TCZ) has been approved for the treatment of rheumatoid arthritis (RA) in patients who respond inadequately or are intolerant to therapy with disease-modifying antirheumatic drugs (DMARDs)." (PMID 33804790, 2021). "Here we used Tocilizumab (Genentech), a humanized monoclonal anti-IL-6R antibody approved by the US Food and Drug Administration (FDA) since 2010 for rheumatoid arthritis as a prototypic inhibitor of the IL-6R signaling pathway." (PMID 34689150, 2021). "Here, we report a case of MRONJ in a patient treated with tocilizumab, a humanized anti-interleukin-6 receptor antibody that effectively treats moderate to severe rheumatoid arthritis in adults." (PMID 33928006, 2021). "Tocilizumab (TCZ; Actemra®), which is a humanized monoclonal antibody that binds and neutralizes IL-6R, resulting in the inhibition of IL-6-mediated signalling, has been used clinically to treat rheumatoid arthritis." (PMID 33806019, 2021). "Tocilizumab (TCZ) was the first humanized anti-interleukin-6 receptor subunit alpha monoclonal antibody licensed to treat rheumatoid arthritis and systemic juvenile idiopathic arthritis." (PMID 35011830, 2021). "Tocilizumab is a humanized monoclonal antibody against interleukin-6 receptor (IL-6R Ab), commonly used as an immunosuppressive in the treatment of rheumatoid arthritis and systemic juvenile idiopathic arthritis." (PMID 32337113, 2020). "For example, IL-6 and its receptor IL-6R monoclonal antibody have been used in the treatment of rheumatoid arthritis and uveitis, and JAK small molecule inhibitors have also been used in the treatment of rheumatoid arthritis and myelofibrosis." (PMID 33384595, 2020). "Sarilumab, another IL-6R inhibitor for rheumatoid arthritis, and siltuximab, a chimeric monoclonal antibody against IL-6, are indicated for multicentric Castleman’s disease." (PMID 33364959, 2020). "We also found evidence for a causal association between plasma IL6R abundance and coronary artery disease (CAD), atopy, and rheumatoid arthritis." (PMID 32628676, 2020). "To date, two monoclonal antibodies targeting either IL-6 (Siltuximab) or the IL-6R are approved for the treatment of the autoimmune Castleman disease and different forms of arthritis (Tocilizumab) or rheumatoid arthritis (Sarilumab)." (PMID 32456348, 2020). "For instance, blockade of IL-6 or its α-receptor (IL-6R) by monoclonal antibodies has been successfully used to treat rheumatoid arthritis." (PMID 32456348, 2020). "Patients with the Ala358 variant of the IL-6R not only show about 2-fold elevated levels of sIL-6R, but they are also protected from inflammatory diseases such as congestive heart disease, abdominal aneurism, and rheumatoid arthritis." (PMID 31694340, 2019).
rheumatoid arthritis (continued). "An IL‐6R‐specific antibody, named tocilizumab, exists and is approved and marketed for human use in patients with rheumatoid arthritis and in patients suffering from cytokine release syndrome after CAR T‐cell therapy." (PMID 31515941, 2019). "IL-6 trans-signaling is driven by ectodomain shedding of the IL-6R and has been shown to be a critical event in inflammatory diseases such as rheumatoid arthritis and inflammatory bowel disease." (PMID 31357561, 2019). "A decade ago, blocking IL-6R signaling with anti-IL-6R antibodies was approved for treatment of rheumatoid arthritis." (PMID 31694340, 2019). "The humanized anti-IL-6Rα antibody Tocilizumab is approved to treat rheumatoid arthritis and juvenile idiopathic arthritis in more than 100 countries." (PMID 31101051, 2019). "Tocilizumab is a monoclonal antibody directed against the interleukin-6 receptor, which is approved for the treatment of moderate-to-severe rheumatoid arthritis." (PMID 29859543, 2018). "A recombinant humanized monoclonal IL-6R antagonist (tocilizumab) has been approved as an anti-inflammatory drug for inflammatory diseases such as rheumatoid arthritis, Castleman’s disease, and systemic juvenile idiopathic arthritis." (PMID 29078808, 2017). "Recently, tocilizumab, a humanized antibody that targets IL6R, was developed and is currently approved for treating rheumatoid arthritis." (PMID 28240269, 2017). "Tocilizumab, a humanized antihuman IL-6 receptor (IL-6R) antibody, is currently available as one of the therapeutically effective reagents against inflammatory diseases such as rheumatoid arthritis." (PMID 28903416, 2017). "Tocilizumab, an inhibitory IL-6R antibody, that is approved for rheumatoid arthritis, juvenile idiopathic arthritis, Castleman's disease, and Crohn's disease, inhibits IL-6 signaling." (PMID 28903416, 2017). "Clinical data also demonstrate the improvement of rheumatoid arthritis by IL-6R blockade despite increased blood IL-6 levels after the administration of MR16-1." (PMID 29078808, 2017). "Tocilizumab, a humanized anti-IL-6R antibody that binds both cell surfaces of IL-6R and soluble IL-6R, is approved for treatment of rheumatoid arthritis as well as systemic juvenile idiopathic arthritis and shows great promise against Crohn disease." (PMID 27129274, 2016). "IL-6R trans-signaling pathway is the critical player of IL-6-mediated pathology in autoimmune conditions such as rheumatoid arthritis, colitis, tissue fibrosis and cancer." (PMID 27330885, 2016). "Recently, anti‐IL‐6R antibodies have turned into the centre of interest for the treatment of autoimmune diseases such as rheumatoid arthritis (RA), systemic onset juvenile idiopathic arthritis (JIA), adult Still's disease and Castleman's disease." (PMID 26739431, 2016). "It was reported that tocilizumab, a humanized anti-IL-6R monoclonal antibody, improved the signs and symptoms of rheumatoid arthritis, juvenile idiopathic arthritis, and Castleman disease." (PMID 27267059, 2016). "Among them, toclizumab targeting the IL-6R is approved for rheumatoid arthritis, juvenile idiopathic arthritis and Castleman disease while sarilumab also targeting the IL-6R is in late stage clinical trials." (PMID 27080032, 2016). "Although IL‐6R blockade results in upregulation of IL‐6 levels 20, this regimen is feasible also as a long‐time therapy, as recently shown in human rheumatoid arthritis patients." (PMID 26739431, 2016). "Several clinical studies have proven that treatment with monoclonal antibodies to IL-6R improves symptoms of rheumatoid arthritis, Castleman’s disease and systemic juvenile idiopathic arthritis." (PMID 27330885, 2016). "A Federal Drug Administration (FDA) approved humanized anti-IL-6R antibody, tocilizumab (Actemra), has shown promise in the treatment of inflammatory diseases particularly rheumatoid arthritis, Crohn’s disease, and Castleman’s disease." (PMID 26268945, 2015).
rheumatoid arthritis (continued). "Tocilizumab (TCZ), an anti-interleukin-6 receptor antibody, is clinically effective against rheumatoid arthritis (RA), and several reports have indicated how TCZ influences a number of mechanisms underlying RA pathogenesis." (PMID 25604867, 2015). "The role of constitutive activation of the IL-6-signaling pathway is well established in inflammation, and an increase in IL-6 and soluble IL-6Rα in the synovial fluid of joints in rheumatoid arthritis patients was shown to correlate with disease progression." (PMID 24415766, 2014). "There have been few reports of anti-interleukin-6 receptor therapy for patients with rheumatoid arthritis complicated with multiple sclerosis." (PMID 25216562, 2014). "Anti-IL-6Rα antibody tocilizumab was the first antagonist of the IL-6-signaling pathway to receive regulatory approval and is currently used for treating rheumatoid arthritis (14, –, 16)." (PMID 24415766, 2014). "This pattern of effects was consistent with IL6R blockade from infusions of tocilizumab (4–8 mg/kg every 4 weeks) in patients with rheumatoid arthritis studied in randomised trials." (PMID 22421340, 2012). "Blockade of the interleukin-6 receptor (IL6R) with a monoclonal antibody (tocilizumab) licensed for treatment of rheumatoid arthritis reduces systemic and articular inflammation." (PMID 22421340, 2012). "Tocilizumab is a humanised monoclonal antibody against the interleukin-6 receptor (IL-6R) that has been approved to be used as an immunosuppressive drug in the treatment of rheumatoid arthritis." (PMID 22075946, 2011). "Future basic and clinical studies using IL-6 receptor blockers such as Tocilizumab (an anti-IL6R used to treat rheumatoid arthritis) are needed to establish a role for IL-6 in the progression of this secondary pathology." (PMID 20222971, 2010). "Surprisingly, the clinical use of anti-IL6 and anti-IL6Rα agent have been limited to rheumatoid arthritis, Castleman’s disease, and systemic juvenile idiopathic arthritis – all of which have been shown to rely largely on the pro-inflammatory effects of IL6 signaling in driving pathogenicity." (PMID 40961077, 2025). "Two drugs targeting IL6R have been approved to treat rheumatoid arthritis." (PMID 38614964, 2024). "Notably, the normalization of T-cell subsets has been observed in rheumatoid arthritis patients who have undergone long-term treatment with anti-TNF or IL-6R blocker therapies." (PMID 37608254, 2023). "Recent studies reported that tocilizumab, the humanized anti-IL-6R antibody clinically utilized for treating rheumatoid arthritis, could be effective in the treatment of cancer." (PMID 37047623, 2023). "Since, the equivalent anti-IL-6R sarilumab has also been approved for rheumatoid arthritis." (PMID 37831074, 2023). "CTAP-associated rheumatoid arthritis risk genes may also be expressed agnostic of CTAP in a given cell type, such as IL6R in myeloid cells." (PMID 37938773, 2023). "The FDA approved the IL-6R monoclonal antibody, Tocilizumab, to treat rheumatoid arthritis." (PMID 36635302, 2023). "Importantly, therapies targeting IL-6 and IL6R are approved for several conditions including rheumatoid arthritis, cytokine release syndrome, giant cell arteritis, and multicentric Castleman disease." (PMID 36599350, 2023). "Here, we assess the impact of continuous anti-IL-6R therapy in patients with rheumatoid arthritis." (PMID 37831074, 2023). "Anti-IL-6 agents have shown potential benefits in inflammatory disorders, but safety concerns, such as gastrointestinal perforations, have been raised based on previous studies with tocilizumab (a monoclonal antibody against IL-6R) in rheumatoid arthritis patients." (PMID 37626745, 2023). "Tocilizumab (TCZ) is a first-in-class recombinant humanized monoclonal antibody against the IL-6 receptor (IL-6R), which has been marketed as a treatment for Castleman’s disease, moderate to severe active rheumatoid arthritis (RA) in adults, and juvenile idiopathic arthritis." (PMID 38357364, 2023).
rheumatoid arthritis (continued). "However, Tocilizumab has failed in phase II clinical trials for IBD due to non-tolerable side effects, including intestinal perforations that were also occasionally observed in patients during anti-IL-6R therapy of rheumatoid arthritis." (PMID 37838173, 2023). "Similarly, CD39+ Tregs efficiently suppress Th17 responses, are dysregulated in rheumatoid arthritis and multiple sclerosis and increase in rheumatoid arthritis patients responsive to methotrexate and following IL-6R blockade with tocilizumab." (PMID 35911690, 2022). "We showed that Tocilizumab (TCZ), an FDA-approved anti-IL-6R antibody for the treatment of patients with rheumatoid arthritis, could reverse tamoxifen resistance in vitro and in vivo." (PMID 33806019, 2021). "Moreover, IL-6R expression is significantly increased on Th17 cells from untreated patients with rheumatoid arthritis (RA)." (PMID 34913099, 2021). "This strategy has been integrated into the treatment of rheumatoid arthritis with high success as well: notably Tocilizumab (Target: IL-6R), Adalimumab (Target: TNFα) and Goliumab (Target: TNFα) are approved and highly successful therapeutics as mono- or combination therapy with DMARDs." (PMID 32082321, 2020). "Particularly, the treatment of Covid19 patients with Tocilizumab, a recombinant humanized monoclonal antibody against the soluble and membrane-bound Interleukin-6 receptor (IL-6R), already approved for rheumatoid arthritis, successfully reduced the mortality rate." (PMID 32974295, 2020). "Tocilizumab (TCZ), a humanized antibody targeting IL-6 receptor (IL-6R), has been licensed for the treatment of rheumatoid arthritis, juvenile idiopathic arthritis, giant cell arteritis, and chimeric antigen receptor T-cell therapy-induced cytokine release syndrome." (PMID 33364959, 2020). "To corroborate the results we obtained using siRNAs with a more clinically relevant agent, we used tocilizumab (TCZ), an IL-6Rα-targeted monoclonal antibody that is FDA approved for the treatment of rheumatoid arthritis and chimeric antigen receptor (CAR) T cell-induced cytokine release syndrome." (PMID 31914141, 2020). "IL-6 is also a therapeutic target for many diseases, and the efficacy of anti-IL-6 receptor (IL-6R) Tocilizumab as a single therapy or in combination with anti-rheumatic drugs in the treatment of moderate to severe rheumatoid arthritis in adults has been demonstrated." (PMID 31970102, 2019). "IL-6 trans-signalling has also been implicated in other diseases such as chronic inflammatory bowel disease and colon cancer, with a humanized monoclonal IL-6R antibody (tocilizumab) currently licensed for use in rheumatoid arthritis and systemic juvenile idiopathic arthritis." (PMID 31395050, 2019). "Moreover, it has been recently suggested that the detection of an IFN signature in peripheral blood is associated with poor response to both B-cell depleting therapy (rituximab) and anti-IL-6R treatment (tocilizumab) in rheumatoid arthritis patients." (PMID 30053827, 2018). "The anti-IL-6R antibody has been successfully used for the treatment of rheumatoid arthritis and inflammatory diseases, and may be applicable for the treatment of other immune-mediated diseases including cancer." (PMID 29078808, 2017). "Increased IL-6 in the body could induce the development of inflammatory diseases, such as rheumatoid arthritis and Crohn's disease, by its binding to IL-6R." (PMID 28953986, 2017). "We present a patient with rheumatoid arthritis and amyloid A amyloidosis who was treated with tocilizumab, a humanized monoclonal antibody against interleukin 6 receptor, resulting in improvement in both proteinuria and gastrointestinal symptoms; however, amyloid deposition remained." (PMID 29287589, 2017). "The anti-IL6R antibody tocilizumab is employed clinically to treat rheumatoid arthritis." (PMID 26512722, 2015).
rheumatoid arthritis (continued). "Therefore, calycosin is a potential candidate as lead compounds for further study in drug development process with IL6R protein against rheumatoid arthritis." (PMID 24991562, 2014). "Interleukin-6 receptor (IL6R) is important in the pathogenesis of rheumatoid arthritis (RA)." (PMID 24991562, 2014). "MR16-1 is a rat anti-mouse IL-6R antibody that competitively inhibits the binding of IL-6 to IL-6R dose-dependently, has a half-life of about 3 days in mice, and exhibits anti-inflammatory properties in rheumatoid arthritis and SCI." (PMID 22369693, 2012). "Clinical trials using neutralizing anti-IL-6R antibody in patients with rheumatoid arthritis and inflammatory pain have been promising, with significant reductions in pain perception and other inflammatory-related symptoms in patients receiving anti-IL-6R antibody." (PMID 21994811, 2010). "For instance, Tocilizumab and Sarilumab, biological agents targeting IL-6Rα, have shown efficacy in moderate to severe rheumatoid arthritis (RA)." (PMID 40002719, 2025). "Similar to IL6R perturbation, IL-6 signaling downregulation through genetic perturbation in IL6 was associated with a lower risk of both polymyalgia rheumatica (odds ratio (OR) per 24% decrease in CRP of 0.76, 95% CI 0.65 to 0.89) and rheumatoid arthritis (OR of 0.87, 95% CI 0.79 to 0.95)." (PMID 40858837, 2025). "Tocilizumab, a humanized monoclonal antibody that inhibits IL-6R signaling, exemplifies this targeted approach in rheumatoid arthritis (RA) treatment." (PMID 41356664, 2025). "This study examined YTHDF2's role in modulating IL‐6R signaling to regulate synovial fibroblast inflammation and bone damage in rheumatoid arthritis (RA)." (PMID 40548546, 2025). "Tocilizumab was the first humanized anti–interleukin-6 receptor (IL-6R) monoclonal antibody to be approved for the treatment of rheumatoid arthritis (RA)." (PMID 39244595, 2024). "However, IL-6R blockade increases the risk of bacterial, viral, and opportunistic infections in rheumatoid arthritis and should therefore not be used in bacterial sepsis." (PMID 38598083, 2024). "A humanized monoclonal antibody (tocilizumab, initially known as MRA) against IL-6R has been produced and used in the treatment of multiple autoimmune and inflammatory diseases including rheumatoid arthritis (RA) and CD." (PMID 38106420, 2023). "Currently, anti-IL-6 or IL-6R therapy is used worldwide in various autoimmune diseases, such as rheumatoid arthritis (RA), juvenile idiopathic arthritis (JIA), systemic sclerosis, and uveitis." (PMID 33816637, 2021). "Tocilizumab (TCZ) is a humanized monoclonal antibody against the interleukin-6 receptor (IL-6R), which was first approved for the treatment of rheumatoid arthritis (RA)." (PMID 34157987, 2021). "In addition, AIFA has authorized a study, due to be coordinated by the Pascale Institute of Naples, to evaluate the efficacy of tocilizumab, a humanized monoclonal antibody against the interleukin-6 receptor (IL-6R), mainly administered for the treatment of rheumatoid arthritis." (PMID 33213445, 2020). "Tocilizumab is an FDA-approved immunosuppressive drug targeting IL-6R that is commonly used for the treatment of rheumatoid arthritis (RA)." (PMID 33072097, 2020). "IL-6 signaling via α- and β-receptors (IL-6R and gp130) is an important biological process for cell differentiation and proliferation, tissue homeostasis, and, when dysregulated, crucial for the onset and progression of certain pathological conditions, such as rheumatoid arthritis and cancer." (PMID 32456348, 2020). "Tocilizumab is an anti-IL-6R monoclonal antibody that is FDA approved for the treatment of rheumatoid arthritis (RA)." (PMID 32899142, 2020). "Tocilizumab, a humanized anti-IL-6 receptor α (IL-6Rα) is widely used in the treatment of a panel of pathologies such as adult and juvenile rheumatoid arthritis (RA) and the systemic form of juvenile idiopathic arthritis in children." (PMID 28861079, 2017).